PRMT1 (protein arginine methyltransferase 1)
Diseases named in the same sentence as PRMT1 in open-access papers (continued):
Sharing a sentence is not in itself a finding about the gene and the disease.
colorectal cancer (continued). "As our data show, PRMT1 could enhance glycolysis in colorectal cancer cells, and we speculated that there might be glycolytic-related enzymes bound to PRMT1." (PMID 38402202, 2024). "In colorectal cancer, the pathophysiological function of PRMT1 is largely unknown although PRMT1 has been examined as a marker of unfavorable prognosis for colon cancer patients." (PMID 33853662, 2021). "C7280948 is a specific inhibitor for PRMT1, which could suppress colorectal cancer progression." (PMID 37558663, 2023). "In colorectal cancer, LPCAT2 regulates the acetylation of Protein Arginine Methyltransferase 1 (PRMT1) at the K145 site, preventing the cytoplasmic transport of PRMT1 in colorectal cancer cells." (PMID 41513612, 2026). "We found that PRMT1 and meR206-PGK1 expression were positively correlated with pS203-PGK1 expression in tissues from colorectal cancer patients." (PMID 38402202, 2024). "PRMT1-mediated H4R3me2a recruits SMARCA4, which promotes colorectal cancer progression by enhancing EGFR signaling." (PMID 33853662, 2021). "We show that PRMT1 and SMARCA4, an ATPase subunit of the SWI/SNF chromatin remodeling complex, act cooperatively to promote colorectal cancer (CRC) progression." (PMID 33853662, 2021). "Although K145 acetylation of PRMT1 has been reported in colorectal cancer (CRC) cells, our mass spectrometry analysis detected no acetylation at K134/K145." (PMID 40884268, 2025). "In colorectal cancer, GSK3368715 exhibits significant antitumor effects by targeting PRMT1." (PMID 39826691, 2025). "A recent study revealed that PRMT1-mediated NONO arginine methylation at R251 in colorectal cancer cells." (PMID 37737256, 2023). "Our findings show that PRMT1 and meR206-PGK1 may become promising predictive biomarkers for the prognosis of patients with CRC and that arginine methyltransferase inhibitors have great potential in colorectal cancer treatment." (PMID 38402202, 2024). "Besides, PRMT1 could enhance the oncogenic arginine methylation of NONO in colorectal cancer via asymmetrically demethylating R251 of NONO." (PMID 37558663, 2023).
leukemia (24 papers, 2012 to 2025). A malignant (clonal) hematologic disorder, involving hematopoietic stem cells and characterized by the presence of primitive or atypical myeloid or lymphoid cells in the bone marrow and the blood. "The importance of PRMT1 in leukemia has been shown in FLT3-ITD, AML1-ETO, and MLL-EEN-associated acute myeloid leukemia and lymphoid leukemia." (PMID 40801789, 2025). "To assess the effects of Prmt1 loss on the propagation of leukemia, we transduced BM cells from 5‐FU‐treated Prmt1fl/fl; Cre‐ERT2 or Prmt1fl/fl mice with BCR‐ABL‐GFP retrovirus and transplanted them into sublethally irradiated recipients." (PMID 39668478, 2025). "The results showed that tamoxifen‐induced Prmt1 loss blocked leukemia development and prolonged the survival of CML mice (median survival: Prmt1fl/fl vs Prmt1fl/fl; Cre‐ERT2 was 14.5 days vs not reached after monitoring for 60 days)." (PMID 39668478, 2025). "Genetic loss of Prmt1 or pharmacological inhibition of PRMT1 remarkably blocked leukemia development, eliminated LSCs, and impaired the self‐renewal of LSCs in CML mice." (PMID 39668478, 2025). "Consequently, the suppression of fatty acid oxidation reduces propionylated histones, meaning that metabolic reprogramming by PRMT1 also causes epigenetic changes during leukemia progression." (PMID 40001488, 2025). "PRMT1 causes leukemia cells’ heavy dependency on glucose consumption." (PMID 40801789, 2025). "Targeting PRMT1 is effective in treating leukemia with splicing factor mutations." (PMID 40801789, 2025). "Interestingly, only a subpopulation of 6133 cells expressing high levels of Prmt1 caused leukemia when transplanted into congenic mice." (PMID 40801789, 2025). "Moreover, SRSF1 and PRMT1 were associated with each other in leukemia cells in vivo." (PMID 22839530, 2012). "This indicates that PRMT1 assists leukemia cells in adapting to the bone marrow niche necessary for leukemia initiation, suggesting that leukemia stem cells likely express high levels of PRMT1." (PMID 40801789, 2025). "(E) Schematic for inducing leukemia through the intravenous injection of 6133 or 6133/PRMT1 cells into sub-lethally irradiated recipient mice (n = 7)." (PMID 40801789, 2025). "Taken together, the in vitro and in vivo data suggest that PRMT1-mediated metabolic reprogramming renders leukemia cells highly dependent on glucose." (PMID 40801789, 2025). "Genetic deletion of Prmt1 blocked leukemia development and impaired the self‐renewal of LSCs in CML mice." (PMID 39668478, 2025). "The protein level of PRMT1 was obviously decreased in splenic leukemia cells from Prmt1 KO CML mice relative to WT CML mice." (PMID 39668478, 2025). "Consistently, PRMT1 accelerated glucose consumption and led to the accumulation of lactic acid in the leukemia cells." (PMID 40801789, 2025). "MS023 treatment inhibited the methyltransferase activity of PRMT1 in leukemia cells from CML mice as reflected by the decreased protein level of H4R3me2a." (PMID 39668478, 2025). "Closed symbols represent mice transplanted with 6133/PRMT1 cell-induced leukemia, while the open square indicates a control wild-type mouse without leukemia." (PMID 40801789, 2025). "PRMT1 overexpression in splenic leukemia cells from secondary CML mice was confirmed by Western blotting analysis." (PMID 39668478, 2025). "Tamoxifen treatment effectively reduced PRMT1 expression in leukemia cells from Prmt1fl/fl; Cre‐ERT2 CML mice." (PMID 39668478, 2025). "Genetic deletion of Prmt1 delayed leukemia development, eliminated LSCs, and impaired the self‐renewal of LSCs in CML mice." (PMID 39668478, 2025). "Taken together, these results indicate that PRMT1 is required for the propagation of leukemia and self‐renewal of LSCs." (PMID 39668478, 2025). "Consistently, the mRNA expression of PRMT1 was higher in leukemia stem/progenitor cells (LSPCs) sorted from individuals with CML (CML CD34+) than in hematopoietic stem/progenitor cells (HSPCs) sorted from healthy donors (normal CD34+)." (PMID 39668478, 2025).
leukemia (continued). "Given that E84-high cells can initiate leukemia, we introduced PRMT1 into 6133 cells (aka 6133/PRMT1 cells) using a lentivirus vector." (PMID 40801789, 2025). "Using this leukemia mouse model, we report here that the elevated level of PRMT1 maintains the leukemic cells via upregulation of glycolysis and that leukemia cells with high PRMT1 expression are vulnerable to the inhibition of fatty acid metabolic pathways." (PMID 40801789, 2025). "The data suggest that leukemia cells with elevated levels of PRMT1 expression can utilize short-chain fatty acids to compensate for their need for glucose." (PMID 40801789, 2025). "PRMT1, the most predominant arginine methyltransferase, plays a critical role in tumorigenesis, especially in hematological malignancies, including leukemia and multiple myeloma (MM)." (PMID 39668478, 2025). "This study indicates that PRMT1 deletion delays the initiation and propagation of leukemia as well as impairs the self‐renewal of CML LSCs." (PMID 39668478, 2025). "Collectively, these data demonstrate that PRMT1 is critical for sustaining Rbm15-MKL1-initiated leukemia in mice, and pharmacological targeting of PRMT1 represents an effective strategy for treating leukemia." (PMID 40801789, 2025). "The results showed significantly decreased enrichment of PRMT1 and H4R3me2a at the gene promoter region of Rpl29 in leukemia cells from the Prmt1 KO versus WT CML mice." (PMID 39668478, 2025). "Consistently, flow cytometry analysis showed that restoration of Rpl29 rescued the Prmt1 deletion‐mediated reductions of the leukemia burden and proportions of LSPCs in secondary CML mice." (PMID 39668478, 2025). "In summary, PRMT1 is a key epigenetic regulator in leukemia with diverse effects on cell growth and differentiation." (PMID 38326807, 2024). "Chromosomal translocations, such as MLL-GAS7 and MOZ-TIF2, produce abnormal oncogenic fusion proteins, highlighting PRMT1’s significance in leukemia pathogenesis." (PMID 38326807, 2024). "In contrast, LOF of cBAF (Smarcd2 and Smarcb1 knockouts), MLL4-COMPASS (Kmt2d knockout) and Prmt1 pushed leukemia toward basophil and erythroid fates." (PMID 37580596, 2023). "Our research examined the activities of a set of PRMT1 inhibitors of leukemia cell proliferation to develop QSAR models of prediction using molecular topology, linear discriminant analysis, and multilinear regression analysis." (PMID 37569634, 2023). "In the next stage of research, multiple PRMT1 inhibitor compounds should be compiled into a virtual library for computationally pursuing and optimizing antileukemic activity against leukemia cell proliferation." (PMID 37569634, 2023). "We used quantitative structure-activity relationships to computationally screen 17 PRMT1 inhibitors of leukemia cell proliferation." (PMID 37569634, 2023). "High expression of PRMT1 has been linked to poor overall survival in many types of cancers; conversely, inhibition of PRMT1 activity blocks the proliferation of leukemia and solid tumors such as lung, breast, and ovarian cancers." (PMID 36152748, 2022). "In mixed-lineage leukemia (MLL)-rearranged ALL, the methylation of the tyrosine kinase FLT3 on arginine R972 and R973 by PRMT1 controls leukemia cell maintenance in vitro." (PMID 36358861, 2022). "In leukemia cells, PRMT1 methylates and activates FLT3 kinase and FLT3 ITD kinase, which are commonly found in acute myelogenous leukemia." (PMID 36152748, 2022). "PRMT1 can also collaborate with some MLL fusion proteins in MLL leukemia, and the enzyme activity of PRMT1 has been shown to be critical for MLL-mediated transformation." (PMID 35311114, 2022). "The high expression of PRMT1 has been shown to block cell differentiation and propagate leukemia, whereas PRMT4 (CRAM1) and PRMT5 affected RNA splicing in hematological malignancies." (PMID 35565298, 2022). "Among them, the overexpression of PRMT1 has been observed in lung, breast, bladder, colon, and prostate cancer and leukemia." (PMID 29383172, 2017).
leukemia (continued). "As a result, in vivo imaging demonstrated reduced leukemia burdens for mice carrying Prmt1 knockdown leukemic cells." (PMID 26766589, 2016). "Cohorts transplanted with Prmt1 knockdown leukemia cells exhibited increased disease latency and a reduced penetrance compared with the scramble control (log-rank test p < 0.0001)." (PMID 26766589, 2016). "Together, these independent approaches confirm a critical function of Prmt1 in both leukemia initiation and maintenance." (PMID 26766589, 2016). "To further understand the functional role of Prmt1 in other leukemia subtypes, we sought to dissect the roles of Prmt1 in MOZ-TIF2-mediated transformation." (PMID 26766589, 2016). "Similar to the MLL-GAS7 studies, there was strong pressure on select leukemia clones to escape from Prmt1 knockdown as indicated by their re-expression of Prmt1, and Hoxa9 in the leukemic mice received MOZ-TIF2 Prmt1 knockdown cells." (PMID 26766589, 2016). "The PRMT1 inhibitor, MS023, effectively cured this PRMT1-driven leukemia." (PMID 40801789, 2025). "PRMT1 regulates LSCs and leukemia development depending on its methyltransferase activity." (PMID 39668478, 2025). "Overexpression of PRMT1 rendered 6133/PRMT1 cells to increase in a cytokine-independent fashion in cell culture, and recipient mice transplanted with 6133/PRMT1 cells developed leukemia and died within 25 days." (PMID 40801789, 2025). "Notably, only leukemia cells with elevated levels of PRMT1 can be transplanted to initiate leukemia." (PMID 40801789, 2025). "For example, PRMT1-mediated metabolic reprogramming is required for leukemia progression." (PMID 40001488, 2025). "Of note, our analysis found potential therapeutic targets in Npm1c and Flt3ITD leukemia, including Prmt1, which may be amenable to therapeutic exploitation." (PMID 37580596, 2023). "The link between H4R3me2a and activation of gene expression has also been established in the case of leukemia driven by an aberrant MLL1-EEN-Sam68-PRMT1 complex, where PRMT1 activity seems to cooperate with MLL1-driven H3K4 methylation to activate target genes." (PMID 33853662, 2021). "Moreover, PRMT1 is identified as an essential component of mixed lineage leukaemia (MLL) and specific knockdown of PRMT1 suppresses MLL-mediated transformation." (PMID 35582230, 2020). "Interestingly, the only mouse transplanted with Prmt1 knockdown cells that succumbed to leukemia re-expressed high levels of Prmt1 and Hoxa9, suggesting a high selective pressure against Prmt1 knockdown for leukemia development." (PMID 26766589, 2016). "We then tested whether Prmt1 swapping could also rescue leukemogenesis in vivo by transplanting primary HSPC immortalized with WT MOZ-TIF2 or MOZ-TIF2-Prmt1 (MT2ΔN79ΔAD2-Prmt1) into syngeneic mice for leukemia development." (PMID 26766589, 2016). "Similar to Prmt1 in vivo knockdown data, the few leukemias from the mice that received Kdm4c-knockdown cells actually re-expressed high levels of Kdm4c and Hoxa9, indicating a strong growth disadvantage of Kdm4c knockdown leukemia cells." (PMID 26766589, 2016). "Although AMI-408 is an early-phase PRMT1 inhibitor that clearly requires further optimization to improve its potency, these results provide the proof-of-principle experimental data showing in vivo efficacy of pharmacological targeting of Prmt1 for leukemia suppression." (PMID 26766589, 2016). "This is also consistent with the finding that KDM4C is required for PRMT1-independent MLL leukemia." (PMID 26766589, 2016). "When the leukemia cells were treated with DB75 (a PRMT1 inhibitor), RBM15 methylation was reduced." (PMID 26575292, 2015). "In this study, we found that the SRSF1 or PRMT1 expression levels could be influenced by each other in a leukemia cell line." (PMID 22839530, 2012).
leukemia (continued). "Besides, in vivo disease reconstitution assay indicated that the secondary Prmt1‐deleted CML mice had much lower leukemia burden (GFP+ cells) and prolonged survival (median survival: Prmt1fl/fl vs Prmt1fl/fl; Cre‐ERT2 was 21 days vs not reached after monitoring for 65 days)." (PMID 39668478, 2025). "Besides, the recipients which received Prmt1 KO GFP+c‐Kit+ cells exhibited reduced leukemia burden (GFP+ cells) and prolonged survival (median survival: WT vs Prmt1 KO was 24 days vs not reached after monitoring for 39 days) compared with those which received WT GFP+c‐Kit+ cells." (PMID 39668478, 2025). "Thus, dysregulation of PRMT1-–RBM15 pathway might be a common mechanism in leukemia and solid tumors." (PMID 26575292, 2015). "This study reveals for the first time that PRMT1, the predominant enzyme responsible for cellular protein arginine methylation, plays a crucial role in promoting erythroid differentiation in bipotent leukemia cells as well as in human primary CD34+ hematopoietic progenitor cells." (PMID 23483889, 2013). "We also found that expression of SRSF1 and PRMT1 in the Nalm-6 (TEL-AML1 positive) and Reh (TEL-AML1 negative) cell lines could be attenuated with chemotherapy drugs; additionally, SRSF1 and PRMT1 were associated with each other in leukemia cells in vivo." (PMID 22839530, 2012). "For instance, PRMT1-mediated H4R3 methylation enhances protein synthesis, promoting leukemia cell self-renewal and activating the EGFR signaling pathway." (PMID 40393971, 2025). "In conclusion, our results revealed that PRMT1 was required for the function of human primary CML LSCs, the development of leukemia, and the disease reconstitution ability of LSCs in CML mice." (PMID 39668478, 2025). "Collectively, PRMT1 is essential for the initiation of overt AMKL expressing the RBM15-MKL1 fusion protein, and leukemia initiated by 6133/PRMT1 cells in mice resembles several characteristics of human AMKL." (PMID 40801789, 2025). "PRMT1’s interaction with β-Catenin and HOXA9 in LSK-MLL-ENL cells plays a crucial role in mediating leukemia self-renewal, highlighting the significance of the HOXA9/PRMT1 molecular network beyond β-Catenin dependence." (PMID 38326807, 2024). "PRMT1 methylates AML1-ETO9, increasing its transcriptional activity in murine leukemia transformed by this fusion oncoprotein." (PMID 37569634, 2023). "As KDM4C binds to MLL N-terminus region, KDM4C is also required for leukaemia induced by other MLL fusions independent on PRMT1, suggesting a much broader function of KDM4C in maintaining aberrant epigenetic networks in MLL leukaemia." (PMID 27593928, 2017). "The involvements and therapeutic potential of targeting PMTs in human cancer were initially illustrated in MLL leukemia where the recruitments of DOT1L by MLL-AF10 and PRMT1 by MLL-EEN were required for transcriptional deregulation and cellular transformation." (PMID 26766589, 2016). "The roles of PRMT1 in supporting cancer cell proliferation are shown in AML1-ETO and MLL-EEN-initiated leukemia." (PMID 26575292, 2015). "To further probe the importance of PRMT1 enzymatic activity in alternative splicing, we used PRMT1 inhibitor DB75 to treat MEG-01 cells, CMK cells and CMY cells, which all derived from AMKL leukemia patients." (PMID 26575292, 2015). "PRMT1 has been reported to directly methylate RUNX1, a critical transcription factor involved in approximately 30 % of pediatric leukemia cases." (PMID 22839530, 2012). "Restoration of PRMT1WT but not PRMT1E153Q reversed Prmt1 KO‐mediated reductions of the leukemia burden and the percentages of LSPCs in BM and spleen of secondary CML mice." (PMID 39668478, 2025). "All mice that received 6133 cells expressing higher levels of PRMT1 (6133/PRMT1 cells) developed leukemia and died rapidly, while 6133 cells expressing lower levels of PRMT1 did not develop leukemia." (PMID 40801789, 2025).